IL6 (interleukin 6)
Diseases named in the same sentence as IL6 in open-access papers (continued):
Sharing a sentence is not in itself a finding about the gene and the disease.
Insulin resistance (continued). "Second, silver carp and salmon phospholipids contain n-3 PUFA, which can significantly reduce the serum IL-6, TNF-α, and MCP-1 levels of high-fat mice, inhibiting the body’s inflammatory response and thus improving insulin resistance and metabolic syndrome." (PMID 36291067, 2022). "The dietary supplementation of RES increased the litter weight at parturition by 12.53% (p = 0.145), with ameliorated insulin resistance (HOMA-IR), increased triglyceride (TG) levels, and decreased interleukin (IL)-1β and IL-6 levels in serum (p < 0.05)." (PMID 36407549, 2022). "A significant decrease in fasting glycemia (−5%), insulin resistance (−11%), ALP (−8%), glucagon (−13%), IL-6 (−14%), and TNF-α (−20%) was detected." (PMID 35796695, 2022). "The presence of a periodontal infection elevates the plasma levels of TNF-α, IL-6 and C-reactive protein (CRP) and insulin resistance markers such as HOMA-IR in periodontitis patients." (PMID 35327570, 2022). "The M1 macrophages produce pro-inflammatory cytokines, such as Tumor Necrosis Factor (TNF)-α, interleukin IL-6 and MCP-1, which contribute to the development of insulin resistance." (PMID 36501129, 2022). "HDL-C, LDL-C, TC, TG, CRP, TNF-α, and IL-6 levels were abnormal in the HFD group, indicating harm to lipid metabolism and inflammation after a HFD-induced insulin resistance diet." (PMID 35907080, 2022). "It increased the factors involved in insulin resistance, including blood levels of FFA, LDL/HDL ratio, TNF-alpha, IL-6, and HOMA-IR; however, these changes were reversed by metformin and water and alcoholic extracts of AA." (PMID 35145895, 2022). "In this study, the diminished effect of EEI on inflammatory gene expression in liver tissue of HFD-induced insulin resistance and NAFLD rats was clearly observed from the decrease of Tnf and Il6." (PMID 36432581, 2022). "High secretion of IL-6 participates in the pathogenesis of GDM, as it can aggravate insulin resistance in pregnancy." (PMID 36203592, 2022). "Cytokines released by the adipose tissue, such as interleukin-6 (IL-6) and tumor necrosis factor-α (TNF-α), appear to directly link adiposity with insulin resistance." (PMID 35956404, 2022). "Systemic markers such as CRP, TNF-α, and IL-6 play an important role in both the progression of COPD and the development of insulin resistance." (PMID 35628022, 2022). "They secrete pro-inflammatory cytokines (TNF-α, IL-6, IL-1β, IL-12, and MCP-1), which not only have a role in promoting insulin resistance but also recruit other immune cells to the site of inflammation." (PMID 36248900, 2022). "More IL-6 and hs-CRP are produced by the liver, which leads to insulin resistance and endothelial dysfunction." (PMID 35317787, 2022). "M1 ATMs form the “crown like” structure around dead adipocytes and produce TNF-α, IL-6, and CCL2, accelerating chronic inflammation and insulin resistance." (PMID 35885044, 2022). "TNF can induce insulin resistance and synergistically induce vascular endothelial growth factor (VEGF) production with IL1B and IL6 to affect angiogenesis." (PMID 35755045, 2022). "Various circulating cytokines, e.g., interleukin 6 (IL−6) or tumor necrosis factor-alpha (TNF-alpha), seem to be culprits in exacerbating insulin resistance in pregnancy." (PMID 34360631, 2021). "The increased secretions of multiple proinflammatory cytokines and chemokines, such as IL-6, TNF-α, IL-1β, and monocyte chemoattractant protein-1 (MCP-1) in adipose tissue are involved in insulin resistance." (PMID 34043673, 2021). "Omentin-1 serum concentration is negatively correlated to BMI, insulin resistance index (HOMA-IR), fasting insulin, plasma glucose, leptin, TNFα and IL-6." (PMID 33799622, 2021). "Adipo-myokines, such as IL-6 and TNF-α, secreted from muscle cells and adipocytes, if chronically elevated, can induce insulin resistance and consequently other comorbidities." (PMID 33807959, 2021).
Insulin resistance (continued). "Another common denominator in the pathogenesis of insulin resistance, hypertension, and salt sensitivity (SS) is immune activation involving pro-inflammatory cytokines like tumor necrosis factor (TNF)-α, IL-1β, and IL-6." (PMID 34966295, 2021). "Following the infiltration of CD8-positive cytotoxic T cells and the phenotypic change to M1 macrophages, inflammatory adipokines including TNF-α, IL-6, and RETN are produced, leading to insulin resistance." (PMID 34884703, 2021). "Pro-inflammatory factors, like IL-6, TNF-α, MCP-1, also aggravated glucose dysregulation and inhibited normal insulin signaling, resulting in insulin resistance (IR)." (PMID 33778016, 2021). "Intermittent hypoxia and insulin resistance in OSAHS patients can promote the increase of inflammatory markers, including nitric oxide (NO), endothelin-1(ET-1), interleukin-6 (IL-6), and C-reactive protein (CRP)." (PMID 33628835, 2021). "A myriad of inflammatory cytokines including TNF-α, IL-6, and C-reactive protein (CRP), are increased in skeletal muscle under conditions of insulin resistance." (PMID 33922918, 2021). "IL-6 and SOCS3 mediate inflammatory responses and the satiety hormone of leptin, induce dysfunction of Jak-STAT signaling pathway, leading to insulin resistance and lipid metabolic disorders." (PMID 32106651, 2021). "Previous researchers have verified that the decline in the PI3K/Akt pathway following insulin resistance leads to microglial activation and stimulation of the NF-kB signal, which provokes the generation of proinflammatory cytokines such as TNF-α and IL6." (PMID 34366841, 2021). "Insulin resistance has been widely recorded in malignant tumors contributing to cancer cachexia due to chronic exposure to pro-inflammatory cytokines, such as TNF-a, IL-6, and insulin growth factor binding protein." (PMID 33916252, 2021). "In the adipocytes, fatty acid and glucose trigger IRE1A activation - leading to insulin resistance through the JNK signaling cascade, and PERK arm, which triggers the secretion of adipokines, Tissue Necrosis Factor Alpha (TNFA) and Interleukin-6 (IL-6)." (PMID 34124059, 2021). "ROS-caused oxidative stress stimulates the secretion of inflammatory cytokines (such as interleukin-6 (IL-6) and tumor necrosis factor (TNF)-alpha) and adipokines, which leads to insulin resistance and other metabolic disorders." (PMID 33799840, 2021). "Various kinases, which can be stimulated by TNF-α and IL-6, such as Jun NH2-terminal kinase (JNK), an inhibitor of NF-κB kinase (IKK) and protein kinase C (PKC) are candidates that can mediate insulin resistance." (PMID 34069933, 2021). "Inflammatory markers involved in metabolic syndrome (TNF-α, IL-1, IL-6, PAI-1) can upregulate periodontal disease when a persistent periodontal inflammation can exacerbate systemic inflammation, insulin resistance and endothelial dysfunction." (PMID 34187434, 2021). "In particular, high expression of HSP60 induces the release of IL-6 and TNF-α by adipocytes, contributing to the onset of insulin resistance." (PMID 34206506, 2021). "Further, the ADSC-injected mice displayed lower levels of macrophage (F4/80+) infiltration, interleukin-6 (IL-6), and nucleotide-binding oligomerization domain 2 (NOD2) in liver tissue, resulting in improved insulin resistance." (PMID 33957965, 2021). "Studies have shown that IL-6 and TNF-α are secreted from infiltrated macrophages into adipose tissue and have critical roles in MetS, insulin resistance, nonalcoholic fatty liver disease, and atherogenesis." (PMID 34938803, 2021). "T2DM is associated with long-term chronic low-grade inflammation characterized by an increase in some inflammatory markers, such as TNF-α, IL-6, and CRP, contributing to insulin resistance and the pathogenesis of T2DM." (PMID 34955840, 2021). "Elevated levels of IL-6 and TNF-α also induce insulin resistance and promote the development of CHD." (PMID 34824593, 2021).
Insulin resistance (continued). "Recent evidence suggests a positive relationship between inflammatory markers including IL-1β, IL-6, CRP and TNF-α and insulin resistance." (PMID 34078385, 2021). "Galectin 2 is suspected of having an impact on macrophages M1 and M2 by its polarization and releasing interleukin 6 (IL-6) and TNF-α, which generates insulin resistance." (PMID 34769010, 2021). "Interleukin-6 (IL6) is identified as a key mediator of inflammation, fibrosis and glucose metabolism; it is the basis of insulin resistance in patients with T2DM51,52." (PMID 34675276, 2021). "Increase levels of pro-inflammatory cytokines such as IL-1β, IL-6, TNF-α and growth hormone is an important characteristic of peripheral insulin resistance." (PMID 34416903, 2021). "Virulent H. pylori strains induce insulin-regulating gastroduodenal hormones by inducing inflammatory factors IL6, CRP, and chronic inflammation, and ultimately increase insulin resistance." (PMID 34922625, 2021). "Supplementation with vitamin D in obese adolescents resulted in decrease of insulin resistance, while levels of inflammatory markers [CRP, TNF–α, IL–6] remained unchanged." (PMID 32326621, 2020). "In pregnant women, excessive fat mass increases the circulating levels of pro-inflammatory cytokines, IL-6, and tumor necrosis factor- α (TNF-α), among others, which further accentuates pregnancy-induced insulin resistance." (PMID 33374585, 2020). "IL-6 has been shown to activate SOCS-1 and -3 proteins in the liver, thus accompanying insulin resistance." (PMID 32047529, 2020). "Insulin resistance leads to increased release of free fatty acids (FFA) and release of various inflammatory cytokines including tumor necrosis factor- α (TNF-α), interleukin 6 (IL-6), leptin, and resistin." (PMID 33330100, 2020). "Reduced level of adiponectin and increased levels of interleukin-6 (IL-6), tumor necrosis factor-α (TNF-α), free fatty acids, and resistin can reduce insulin-mediated glucose uptake due to insulin resistance." (PMID 32047529, 2020). "Higher circulating C-reactive protein, interleukin 6, and tumor necrosis factor alpha have been reported in PCOS which, through various mechanisms, can contribute to adipocyte dysfunction, insulin resistance, and type 2 diabetes." (PMID 31952348, 2020). "Elevated serum levels of IL-6 in PCOS patients reflect low-grade chronic inflammation, which has been attributed to insulin resistance in PCOS." (PMID 32148541, 2020). "In order to better link the changes in intestinal flora of PCOS model rats with insulin resistance, we measured the serum concentration of HS-CPR, IL-6, and TNF-α." (PMID 32973686, 2020). "The increased production of pro-inflammatory cytokines such as “TNF- α, IL-1β, IL-6, and MCP-1” in turn, triggers chronic inflammatory reactions and enhance insulin resistance." (PMID 33329380, 2020). "The interaction between ox-LDL and Toll-like receptor 4 (TLR4) activates NF-κB path way resulting in elevated expression of pro-inflammatory cytokines including IL-1β, IL-6, and TNF-α which induce insulin resistance." (PMID 32005271, 2020). "Also, vitamin E supplementation resulted in a significant reduction in serum concentrations of IL-6 in RCTs that used α-tocopherol for their intervention and those trials that were performed on unhealthy participants including those with disorders related to insulin resistance." (PMID 33057114, 2020). "It is known that adipose tissue increases the secretion of proinflammatory cytokines, such as IL-6, TNF-α, and leptin, which are closely related to the development of insulin resistance." (PMID 32694929, 2020). "Two studies regarding the effects of pioglitazone and different doses L. casei in diabetic mice showed comparable reductions in insulin resistance, TNF-α and IL-6 at 109 CFU dose." (PMID 33292434, 2020). "Among other “adipokines,” IL-6 and TNF-α are also shown to promote CMS, thus, dysregulation of adipokine synthesis and release plays a critical role in insulin resistance." (PMID 33344519, 2020).
Insulin resistance (continued). "The levels of pro-inflammatory cytokines (TNF-α, IL-1β and IL-6) and the expression of TLR4 were downregulated (P < 0.05), while the insulin resistance index, HOMA-IR showed improvement by GP treatment (P < 0.05)." (PMID 32024509, 2020). "Quercetin-treated female Wistar rats showed decreased levels of IL-1β, IL-6, and tumor necrosis factor (TNF)- α, and decreased insulin resistance." (PMID 32903374, 2020). "Oxidative stress, mitochondrial dysfunction, accumulation of intracellular lipid derivatives, and inflammation (via IL-6 and TNFα) contribute to decreased activation of signaling molecules, including PI3K and AKT, leading to insulin resistance." (PMID 32802136, 2020). "Besides, deteriorated metabolic status influences elevated levels of inflammatory cytokines such as interleukin 6 (IL-6), tumor necrosis factor alpha (TNF-α), C-reactive protein (CRP), and leptin hormone, which may be implicated in insulin resistance and tumor development." (PMID 33238496, 2020). "The excess of adipose tissue increases secretion of inflammatory cytokines such as TNF-alpha and IL-6 that inhibit phosphorylation of insulin receptors (IRS-1), promoting insulin resistance." (PMID 32599690, 2020). "Both IL-6 and TNF-α promote insulin resistance inhibiting lipoprotein lipase (LPL), decreasing triglyceride hydrolysis into free fatty acids, and increasing triglyceride storage in adipocytes, resulting in larger fat cells." (PMID 33643281, 2020). "CSAT+® supplementation reduced blood glucose, Homeostatic Model Assessment of Insulin Resistance (HOMA-IR) and circulating levels of total cholesterol, low-density lipoprotein (LDL) cholesterol (LDL-c), insulin, and interleukin-6 (IL-6)." (PMID 32326269, 2020). "The production of TNF-α and IL-6 cytokines by macrophages leads to increased serine phosphorylation of insulin receptor substrate-1 (IRS-1), resulting in insulin resistance in the muscle and liver." (PMID 33105775, 2020). "Further, to validate the functional impacts of the rs35652124 TT genotype on insulin resistance and wound healing process, we have studied the transcriptional profile of IL-10, TNF-α, and IL-6 in the study cohort based on their genotype." (PMID 32879654, 2020). "Macrophages begin to form so-called crown-like structures in adipose tissue and start to produce the proinflammatory cytokines involved in inflammatory responses and in insulin resistance, such as TNF-α, IL-1β and IL-6." (PMID 31363792, 2019). "Circulating levels of IL-6 and TNF-α are elevated in obese individuals and patients with insulin resistance." (PMID 31398785, 2019). "Visfatin-induced inflammation and insulin resistance were regulated by JAK2/STAT3 and IKK/NF-κB signaling; together with AG490 or Bay 7082, visfatin significantly reduced mRNA levels of IL-6, TNF-α and IL-1β and rescued insulin signaling." (PMID 31396538, 2019). "Fasting plasma glucose, insulin, insulin resistance (HOMA-IR index, IRI), the S-100β protein level, and the inflammatory mediators IL-1β, IL-6 and TNF-α were assessed after surgery (postoperative day (POD) 1 and 3)." (PMID 31092210, 2019). "Not only ASCs but also their conditioned media have been shown to reverse insulin resistance via up-regulation of GLUT-4 expression and reductions in the expression of interleukin 6 (IL-6) and plasminogen activator inhibitor-1 (PAI-1)." (PMID 31620992, 2019). "Compared with normal backfat thickness sows, the excessive backfat thickness sows had increased levels of plasma glucose, IL-6, and TNF-α and homeostasis model assessment insulin resistance values." (PMID 31881697, 2019). "Flavonoids morin, hesperidin, rutin, (rats), and chrysin (mice) were effective in reducing inflammatory cytokines IL-1β, IL-6, and TNF-α in diabetic animals, significantly improving hyperglycemia, glucose intolerance, and insulin resistance." (PMID 30764536, 2019).
Insulin resistance (continued). "In contrast, previous studies have shown that activating the IL6/STAT3 signaling pathway markedly ameliorates liver lipid metabolism, inflammation, and insulin resistance under HFD." (PMID 31949882, 2019). "The present study therefore focused on the relationships of intraocular cytokines (IL-6 and VEGF) with a host of relevant systemic parameters, including hyperglycemia, hypertension, dyslipidemia, smoking, alcohol consumption, insulin resistance, and obesity." (PMID 31396410, 2019). "Thus, suppression of the level of serum IL-6 could ameliorate the insulin resistance complications." (PMID 31597283, 2019). "Our results indicate that high-glucose load leads to glucose intolerance with insulin resistance through impairment of GLP-1 secretion, increase of blood glucose levels via activating TLR4 and increasing levels of IL-6 and TNF-α in mice." (PMID 31138952, 2019). "Physical activity increases the secretion of interleukin-6 (IL-6) from muscle cells, which has anti-inflammatory effects through inhibition of TNF-a and IL-1b, and reduces TNF-induced insulin resistance." (PMID 30867683, 2019). "Resistin could be a link between insulin resistance and obesity; its release reduces peripheral insulin sensitivity, increases endogenous glucose production by the liver, induces insulin resistance, and stimulates proinflammatory cytokines (e.g., IL-6 and tumor necrosis factor (TNF)-α)." (PMID 31671697, 2019). "Obese pre-DM patients showed high values of glucose, insulin resistance (HOMA-IR), C reactive protein (CRP), nitrotyrosine, tumor necrosis factor-α (TNF-α) and interleukin 6 (IL-6), and low values of insulin (p < 0.05)." (PMID 30845774, 2019). "After 6 weeks, Alanine aminotransferase (ALT), glucose, insulin, HOMA IR (Homeostatic Model Assessment for Insulin Resistance), FFA (free fatty acids), Tumor necrosis factor alpha (TNF α), IL6, IL1B levels were measured in blood." (PMID 31496048, 2019). "Serum levels of IL-6 and TNF-α and insulin resistance were significantly higher in cases than the controls." (PMID 30635365, 2019). "It was found that insulin resistance (HbA1c, HOMA-IR) and inflammation (hsCRP, IL-6) circulating biomarkers decreased, while reproductive biomarkers (LH, FSH, SHBG) increased significantly." (PMID 31440472, 2019). "Compared with placebo vitamin D supplementation:↓ IL-6 and ↑ hs-CRPNo changes in TNF-α and insulin resistance." (PMID 31068933, 2019). "Elevated levels of pro-inflammatory biomarkers such as TNF-α, interleukin-6 (IL-6) and interleukin-8 (IL-8), and C-reactive protein (CRP) have all been reported in various insulin resistance states." (PMID 29955954, 2019). "Carnitine has been reported as highly efficient in the downregulation of pro-inflammatory cytokines TNF-α and IL-6 in murine models of cancer cachexia, liver fibrosis and in blocking TNF-α-induced insulin resistance in skeletal muscle cells." (PMID 31718684, 2019). "This is because IL-17 also induces the production of IL-6 and TNF-alpha, the cytokines with marked proinflammatory effects that play an important role for the development of insulin resistance." (PMID 30862094, 2019). "Elevated levels of interleukin 6 (IL-6), C-reactive protein (CRP) and fibrinogen in PD increase insulin resistance." (PMID 30477167, 2018). "Thus, it is possible that upregulation of IL-6 may not be causative in HFD-induced insulin resistance but persistent decreases in IL-6 may be sufficient to improve insulin sensitivity in mice fed HFD." (PMID 29562620, 2018). "Increased level of inflammatory cytokines, such as IFN-γ, IL-1β, IL17A, IL6, and TNF-α, is also related to insulin resistance, and increased anti-inflammatory cytokines can improve glucose metabolism which regulates insulin sensitivity." (PMID 29541033, 2018).